ADA2 (adenosine deaminase 2)
Diseases named in the same sentence as ADA2 in open-access papers (continued):
Sharing a sentence is not in itself a finding about the gene and the disease.
cutaneous vasculitis (2 papers, 2021 to 2022). Inflammation of the blood vessel wall characterized by palpable purpura. "In a case of ADA2 deficiency due to a mutation in the CECR1 gene, the patient presented with intermittent fever, cutaneous vasculitis, muscle pain, and muscle inflammation." (PMID 36225941, 2022).
empyema (2 papers, 2017 to 2022). An accumulation of pus in a body cavity, usually the pleural space. "ADA-2 is mainly activated in tuberculous pleural effusion; conversely, low ADA-2 activities are observed in other diseases, such as neoplastic exudate, empyema, and parapneumonic exudate." (PMID 36131272, 2022). "ADA-2, which is mainly expressed in and released from mononuclear cells and macrophages, correlates with intracellular infection such as TPE, and high levels of ADA-1 are always present in empyema." (PMID 29202740, 2017).
endothelial dysfunction (2 papers, 2021 to 2023). In vascular diseases, endothelial dysfunction is a systemic pathological state of the endothelium (the inner lining of blood vessels) and can be broadly defined as an imbalance between vasodilating and vasoconstricting substances produced by (or acting on) the endothelium. "TNBC patients also demonstrated positive associations between plasma ADA2 activity and pro-tumor M2 macrophage markers, as well as between ADA1 activity and endothelial dysfunction or inflammatory parameters." (PMID 33916440, 2021). "In our previous study, we have shown that deoxycoformycin (ADA1 and ADA2 inhibitor) counteracted BC-induced endothelial dysfunction, decreased 4T1 BC cell adhesion and transmigration through the endothelial cell layer, and suppressed migration and invasion of murine and human BC cells." (PMID 33916440, 2021). "In patients, we demonstrated a long-term microvascular and endothelial dysfunction together with the decreased concentration of serum ADA1-complexing protein CD26 and ADA2 isoenzyme activity." (PMID 37685949, 2023).
hairy cell leukaemia (2 papers, 2008 to 2023). "Primary etiology of PAN can be idiopathic; however, secondary causes have been linked to chronic Hepatitis B and C infection, Hairy Cell Leukemia, and Adenosine Deaminase 2 deficiency." (PMID 37266725, 2023). "The specific ADA2 inhibitor 2'-deoxycoformycin (pentostatin), primarily used to treat hairy cell leukaemia, has seen increasing attention as an immunosuppressant." (PMID 18847498, 2008).
head and neck cancer (2 papers, 2022 to 2025). A primary or metastatic malignant neoplasm affecting the head and neck. "We developed ELISA-based assays for quantitative ADA2 detection in biological fluids that can diagnose head and neck cancers and ADA2 deficiency (DADA2) using saliva samples." (PMID 40936927, 2025). "Therefore, we decided to analyze ADA2 concentration in saliva samples from head and neck cancer patients." (PMID 35967411, 2022). "Therefore, more studies are required to analyze ADA2 concentration at different stages of cancer to prove that ADA2 could be used as a predictive marker to diagnose specific head and neck cancers." (PMID 35967411, 2022). "In contrast, the concentration of ADA2 increases in the serum of patients with large granular leukocyte leukemia (LGLL) and patients’ saliva with head and neck cancer." (PMID 35967411, 2022).
hepatic disorders (2 papers, 2020 to 2025). "Clinical manifestations of deficiency of ADA2 (DADA2) include hypogammaglobulinemia, recurrent infections, bone marrow aplasia, pure red cell aplasia, neutropenia, liver disease, neurological impairments, and vasculopathy of small- and medium-sized arteries." (PMID 32184784, 2020). "We also describe the clinical features of liver disease in some monogenic forms of PID included in the clinical spectrum of CVID as ICOS, NFKB1, NFKB2, CTLA-4, PI3Kδ pathway, ADA2, and IL21-R genetic defects." (PMID 32184784, 2020).
meningitis (2 papers, 2023 to 2025). A disorder characterized by acute inflammation of the meninges of the brain and/or spinal cord. "Notably, 35 were upregulated compared to controls, particularly A2M and ADA2, which were more upregulated than in other meningitis types." (PMID 41181321, 2025). "A2M, ADA2, and PDGFB, as cytokine receptors, displayed higher or lower levels compared to the other three meningitis types." (PMID 41181321, 2025).
ovarian carcinoma (2 papers, 2020 to 2023). A malignant neoplasm originating from the surface ovarian epithelium. "The identification of NCOR2 as one of the top eight genes responding to combination therapy in ovarian cancer is significant because like BDP1, NCOR2 contains a SANT domain (SWI3, ADA2, N‐Cor, and yeast TFIIIB BDP1 proteins) (reviewed in17)." (PMID 36305848, 2023).
rheumatic diseases (2 papers, 2020 to 2022). "Given the pleiotropic manifestations of DADA2, it is important to include ADA2 gene in various customized NGS panels used for evaluation of haematological, immunological, and rheumatological disorders." (PMID 35592317, 2022).
breast invasive carcinoma (1 paper, 2022). "However, high ADA2 expression showed a favorable prognosis in breast invasive carcinoma (BRCA), cervical squamous cell carcinoma and endocervical adenocarcinoma (CESC), HNSC, KIRC, KIRP, LUAD, OV, PAAD, sarcoma, and THYM." (PMID 35663977, 2022).
Childhood-onset polyarteritis nodosa (1 paper, 2019). "Childhood-onset polyarteritis nodosa is an autosomal recessive disease caused by biallelic mutations of CECR1 (cat eye syndrome chromosome region, candidate 1), encoding extracellular deaminase 2 (ADA2) that deaminates adenosine to inosine." (PMID 31379837, 2019).
combined immunodeficiency syndrome (1 paper, 2014). A combined immunodeficiency in which other clinical features are present in other organ systems in addition to immunodeficiency. "The ADA1 deficiency causes severe combined immunodeficiency syndrome and ADA2 protein may act as a growth factor and has adenosine deaminase activity converting adenosine and deoxyadenosine to inosine and deoxyinosine, respectively." (PMID 24959203, 2014).
dengue (1 paper, 2022). "ADA2 also removes adenosine from bite site and aids in a prolonged blood-feeding and has been shown to partially enhance dengue and Zika virus infection in human THP-1 cells." (PMID 36070318, 2022).
G6PD deficiency (1 paper, 2021). An X-linked genetic condition caused by alterations in the gene G6PD that result in moderately to severely decreased activity levels of the enzyme glucose-6-phosphate dehydrogenase. "In the patients with ADA2 deficiency and G6PD deficiency, disease specific consultation was initiated." (PMID 34992599, 2021).
gastrointestinal infection (1 paper, 2018). "This underlined the role of ada2 as a major regulator of C. glabrata virulence beyond ROS defenses in the context of gastrointestinal infection." (PMID 29535147, 2018).
Genital ulcers (1 paper, 2026). "Similarly, mutations in the ADA2 gene, underlying DADA2 disease, could also lead to recurrent oral/genital ulcers and other BD-like symptoms, complicating the diagnostic process and underscoring the need for genetic testing in atypical cases." (PMID 41562716, 2026).
hypoglycaemia (1 paper, 2014). "We can hypothesize that gene dosage alterations of GAB4 and ADA2 and their possible functional interactions could be subject of changes in carbohydrate metabolism and these are likely the cause of hypoglycaemia susceptibility of the presented patient." (PMID 24959203, 2014).
kidney cancer (1 paper, 2025). Primary or metastatic malignant neoplasm involving the kidney. "The changes in adenosine deaminase (ADA1 and ADA2) activity have been detected in various types of cancer cells, including breast, gastric, bladder, colon, and kidney cancer cells." (PMID 39941076, 2025).
laryngeal carcinoma (1 paper, 2022). Carcinoma that arises from the laryngeal epithelium. "The highest difference in ADA2 concentration was detected in patients with laryngeal carcinoma and tonsil cancer groups." (PMID 35967411, 2022).
leishmaniasis (1 paper, 2020). Infectious disease that is transmitted through the bite of hematophagous female phlebotomine sand flies. "However, salivary tADA, as well as both isoenzymes ADA1, and ADA2, were statistically higher in the dogs with leishmaniasis, showing moderate correlation with serum ferritin (r = 0.60, P < 0.01, for tADA; r = 0.56, P < 0.05, for ADA1; and r = 0.63, P < 0.01, for ADA2)." (PMID 33046093, 2020).
LGL leukemia (1 paper, 2022). "Since ADA2 is significantly increased in the LGLL, our data suggest that ADA2 deficient patients have another type of LGL leukemia." (PMID 35967411, 2022).
Lymphadenopathy (1 paper, 2025). Enlargement (swelling) of a lymph node. "Finally, in patients with deficiency of adenosine deaminase 2 (DADA2, caused by CECR1 mutations), splenomegaly is seen in 30% and lymphadenopathy in about 10% of cases, and patients can exhibit ALPS-like phenotypes." (PMID 40944054, 2025).
multiple sclerosis (1 paper, 2023). A progressive autoimmune disorder affecting the central nervous system resulting in demyelination. "The authors have proposed that the increased ADA1/ADA2 ratio in patients may lead to ADA1-mediated proinflammatory processes and to a decrease in ADA2-dependent neuroprotective effects, promoting multiple sclerosis." (PMID 37512494, 2023).
myelofibrosis (1 paper, 2024). A partial or complete replacement of the bone marrow stroma by fibrous tissue. "Previously, a bicytopenic ADA2 deficient patient was reported with myelofibrosis." (PMID 39161369, 2024).
Nephropathy (1 paper, 2021). A nonspecific term referring to disease or damage of the kidneys. "Several predictors were consistent with the latest medical research: fibrinogen, plasma albumin, hematocrit for nephropathy, and adenosine deaminase-2 for retinopathy." (PMID 34098959, 2021).
pancreatic cancer (1 paper, 2021). "Here, we demonstrated that low TLR1 and ADA2 expression play vital roles in pancreatic cancer immunity and can both mediate immune cell infiltration to affect tumor immune status." (PMID 34654352, 2021). "Prognostic signature containing four IRGs (ADA2, TLR1, PTPN6, S100P) was constructed with good predictive performance; in particular, S100P played a significant role in the immune microenvironment, and tumorigenesis of pancreatic cancer." (PMID 34654352, 2021). "In this study, we constructed an immune-related prognostic signature based on four immune-related genes (ADA2, TLR1, PTPN6, and S100P) that displayed good predictive ability for overall survival and analyzed the infiltration of corresponding immune cells in patients with pancreatic cancer." (PMID 34654352, 2021). "Although the immune mechanisms of ADA2 and TLR1 have been studied in some tumors, they have not yet been studied in pancreatic cancer." (PMID 34654352, 2021).
periodic fever syndrome (1 paper, 2023). Fevers of unknown etiology recurring over months or years. "However, it is unknown if anti-G-CSF therapy might also be beneficial in hyper-IgD with periodic fever syndrome, deficiency of adenosine deaminase-2 or other autoinflammatory conditions." (PMID 36997670, 2023).
supraglottic carcinoma (1 paper, 2022). "While patients with supraglottic carcinoma had similar values of ADA2 to the control group, some of the patients from the other groups had a significantly higher concentration of ADA2." (PMID 35967411, 2022). "Hence, ADA2 could be a more suitable marker for glottic, hypopharyngeal, and tonsil carcinomas than supraglottic carcinoma." (PMID 35967411, 2022).
tonsil cancer (1 paper, 2022). A primary or metastatic malignant neoplasm that affects the tonsil. "Indeed, the combined samples from patients with hypopharyngeal, glottic, and tonsil carcinomas have significantly higher ADA2 concentrations than healthy controls." (PMID 35967411, 2022).
type 1 interferonopathies (1 paper, 2024). "We also compared the cumulative ISG scores of our patients with published data for patients with type 1 interferonopathies (T1Is) and deficiency of adenosine deaminase 2 (DADA2)." (PMID 39403923, 2024).
upper respiratory tract infections (1 paper, 2021). "Lower and upper respiratory tract infections, both viral and bacterial, were presented in most ALPS-like patients with Tregs defect, ADA2 and CARD11 GOF patients." (PMID 34447369, 2021).
vasculopathy (26 papers, 2016 to 2026). "Deficiency of ADA-2 can lead to vasculopathy and inflammation through the macrophages and the polarization of monocytes onto proinflammatory cells, resulting in damage to the endothelial integrity." (PMID 35163523, 2022). "ADA2 mutation disrupts the enzyme’s conversion of adenosine and 2′-deoxyadenosine, leading to neutrophil activation, immune dysfunction, vasculopathy, and catalytic dysfunction, resulting in elevated adenosine levels, leading to inflammation, tissue damage, and fibrosis." (PMID 39239002, 2024). "ADA-2 deficiency may compromise endothelial integrity while polarizing macrophage and monocyte subsets toward proinflammatory cells, thus establishing a vicious circle of vasculopathy and inflammation." (PMID 34133513, 2021). "Human ADA2 deficiency (DADA2) is an inborn error of immunity with a broad clinical phenotype, which encompasses vasculopathy and hemato-immunological features." (PMID 40864493, 2025). "Deficiency of adenosine deaminase 2 is associated with CECR1 mutations and causes a PAN-like vasculopathy and autoinflammatory features." (PMID 30154798, 2018). "Deficiency of adenosine deaminase 2 (DADA2), stimulator of interferon genes (STING)-associated vasculopathy with onset in infancy (SAVI), and haploinsufficiency of A20 (HA20) are the recently defined monogenic vasculitides." (PMID 30154798, 2018). "However, it is worth mentioning that all four patients in this cohort with residual ADA2 levels above 1 U/L (patient 3, 7, 8 and 14) exhibited inflammatory vasculopathy features." (PMID 37277582, 2023). "Here we describe the case of an ADA2 deficiency patient carrying a novel frameshift variant – c.464del (p.Pro155Hisfs*29) – in the ADA2 gene and exhibiting a predominant phenotype of vasculopathy with no haematological manifestations." (PMID 36528591, 2022).
infection (20 papers, 2007 to 2025). The state of being infected such as from the introduction of a foreign agent such as serum, vaccine, antigenic substance or organism. "The biochemical test is highly sensitive for the identification and/or confirmation of DADA2 patients; however, ADA2 protein activity in carriers of a monoallelic ADA2 variant is variable and may be influenced by age and infection status." (PMID 35095905, 2021). "On the other hand, deletion of Ada2 or Ada3 also significantly reduced the lethal action following infection by injection." (PMID 37052485, 2023). "Our results also demonstrated the indispensability of Ada2 and Ada3 in host infection and their role as vital virulence factors in B. Bassiana." (PMID 37052485, 2023). "Some of the SGPs identified in the current study were previously shown to play essential roles in virus transmission or infection, including ADA2, D7 proteins (AAEL006424 and AAEL006417), apyrase, AaVA-1, and NeST1." (PMID 36070318, 2022). "ADA2 exists in monocytes-macrophages and resists immune suppression induced by elevation of adenosine at the time of infection." (PMID 36124285, 2022). "We propose that ADA2 orchestrates the response of C. glabrata against ROS-mediated immune defenses during infection." (PMID 29535147, 2018). "The histone acetyltransferase Gcn5 and the transcription coactivator Ada2 have both been shown to be required for successful infection of mice when studied in the H99L background." (PMID 29263343, 2017). "Given the increasing evidence of the relevance of ADA1 and ADA2 in immunity, these proteins should be further characterized as biomarkers for early life immune ontogeny as well as during responses to immune perturbation such as vaccination or infection." (PMID 34122398, 2021). "Moreover, Ada2 is suggested to orchestrate C. glabrata against ROS-mediated immune defenses during infection." (PMID 31091716, 2019). "Finally, in wild type (w1118) larvae with functioning Duox, ada2 overexpression strain was able to persist and expand three hours after infection while the fungal load of wild type C. glabrata decreased." (PMID 29535147, 2018). "Indeed, the Phytophthora sojae effector PsAvh23 binds the ADA2 subunit of SAGA complex and interrupts the interaction between ADA2 and GCN5, thus leading to the dysregulation of defense-related genes and increased soybean plant susceptibility to the pathogen infection." (PMID 36262654, 2022). "Therefore, it is still possible that the concentration of ADA2 may depend on the type of infection (viral or bacterial), and thus further investigations are required." (PMID 35967411, 2022). "However, since the route of infection was different our hypothesis is that GI vs. systemic immunity may influence the virulence outcome of ada2 mutants." (PMID 29535147, 2018). "Thus, how ADA1, ADA2, and total ADA change during the first week of life and subsequent months of life, when the immune system of neonates and infants undergo dramatic immunologic changes, are most susceptible to infection, and receive the greatest number of vaccines, is still unknown." (PMID 34122398, 2021).